MMP9 (matrix metallopeptidase 9)
Diseases named in the same sentence as MMP9 in open-access papers (continued):
Sharing a sentence is not in itself a finding about the gene and the disease.
breast carcinoma (continued). "In previous studies, highly expressed FN, MMP-2, and MMP-9 trigger cell invasion and migration in several human carcinoma cells, including breast cancer cells." (PMID 26637807, 2016). "To further confirm the key role of MMP-9 in UDP-induced breast cancer cell metastasis, we treated the cells with UDP and MRS2578 or an MMP-9 inhibitor." (PMID 27074554, 2016). "In the current study, in vitro 4T1 cell culture results revealed that HEGU and licoricidin directly inhibit the migration of 4T1 mammary cancer cells as well as the secretion of MMP-9 and VACM-1." (PMID 27314329, 2016). "The existing researches suggest that the high expression of gelatinase A and B (MMP2 and MMP9) promote the metastasis of breast cancer." (PMID 26674531, 2015). "We now show that morphine prevents the increase in MMP-9 elicited by the cross talk between macrophages and breast cancer cells." (PMID 26078009, 2015). "High expression of MMP-9 and MMP-2 were associated with lymph node metastasis as well as with poorer survival in breast cancer." (PMID 25888829, 2015). "At sub-lethal concentrations, AP inhibits breast cancer cell migration and invasion via the downregulation of MMP-9 expression levels." (PMID 25374279, 2015). "Overall, they identified Rab40b GTPase as the key regulator in MMP-2 and MMP-9 transport and targeting to the plasma membrane in the breast cancer invasion process." (PMID 25629807, 2015). "Increased MMP activity results in both matrix remodeling and release of chemokines, cytokines and growth factors trapped within the ECM, promoting EMT process-KLF8-to-MMP9 signaling that promotes human breast cancer invasion." (PMID 26674531, 2015). "Inhibition of Trx1 activity has been shown to decrease MMP-9 expression via suppression of NF-кβ activity and expression of NF-кβ subunits, p50 and p65, in breast cancer cells." (PMID 25945832, 2015). "ανβ3-OPN interaction promotes cancer cell migration and invasion in prostate and breast cancer as well as in chondrosarcoma where OPN-ανβ3 binding leads to MMP-9 up-regulation through the FAK/MEK/ERK/NF-Κβ pathway." (PMID 25629807, 2015). "High levels of MMP-9 are known to promote breast cancer invasion and migration to distant tissue sites and downregulation of MMP-9 has been shown to be an effective mechanism to attenuate metastasis." (PMID 26588686, 2015). "While the MMP arrays are able to detect other MMPs, we focused on MMP9 due to the significant impact it has on breast cancer cell invasion and metastasis." (PMID 25605249, 2015). "This is especially true considering a paper by Wang that demonstrated KLF8’s ability to promote human breast cancer cell invasion and metastasis by transcriptional activation of MMP9." (PMID 25853515, 2015). "MMP-9 expression levels are highly correlated with breast cancer cell invasion and agents that downregulate MMP-9 have been observed to inhibit tumor invasion." (PMID 25374279, 2015). "High expression of MMP-1 (P=0.00012), and MMP-9 (P=0.00022) is predictive of lower RFS in endocrine treated ER+ human breast cancer patients." (PMID 28721370, 2015). "Higher levels of MMP-9, S100A8 and S100A9 transcripts were each significantly associated with worse relapse-free survival over a 20-year interval when all breast cancers were considered." (PMID 25633981, 2015). "Taken together, our results demonstrate that the TSP50 regulation of MMP9 expression through NF-κB signaling is critical for human breast cancer cell invasion." (PMID 25811800, 2015). "Neutrophil secreted MMP-9 is often complexed with NGAL and circulating levels of NGAL or NGAL/MMP-9 complex have been associated with breast cancer and kidney disease." (PMID 25948887, 2015). "It was found that estradiol and TAM regulate MMP-2, MMP-9 and extracellular endostatin in ER + PR + human breast cancer cells and in vivo." (PMID 26526196, 2015). "Cathepsin G-mediated activation of MMP–9 at the tumor-bone interface promotes bone destruction in breast cancer." (PMID 26440411, 2015).
breast carcinoma (continued). "In vitro, PMS can inhibit the proliferation, migration and invasion of MDA-MB-231 human breast cancer cell line and 4T1 mouse breast cancer cell line by decreasing MMP9 and MMP2 activity." (PMID 26674531, 2015). "NDRG2 also inhibits the metastatic potentials of breast cancer cells through inducing bone morphogenetic protein 4 and subsequent suppression of MMP-9 expression." (PMID 25889839, 2015). "In a xenograft tumor model of prostate or breast cancer, curcumin also showed high antimetastatic effect by suppressing the expression of MMP-9, NF-κB, and cyclooxygenase-2." (PMID 26656720, 2015). "Collectively, these results strongly suggest that the increase of MMP9 expression by TSP50 through NF-κB signaling has a critical role in promoting human breast cancer invasion and metastasis." (PMID 25811800, 2015). "Not surprisingly, MMP9 expression caused a significant enhancement of MCF7 cell invasion, demonstrating the direct role MMP9 expression has on breast cancer cell invasion." (PMID 25605249, 2015). "So we supposed PinX1 suppress migration and invasion of breast cancer cells by regulating MMP-9 expression and activity." (PMID 25888829, 2015). "For example, KLF8 was shown to stimulate the invasion of breast cancer cells through the induction of the matrix metalloproteinase gene MMP-9." (PMID 26320172, 2015). "Our assessment of MMP9 expression in invasive breast cancer cells showed that PRMT7 knockdown caused a significant decrease in MMP9 mRNA levels, secreted MMP9 protein amounts and decreased enzymatic activity." (PMID 25605249, 2015). "PinX1 suppressed breast cancer migration and invasion by inhibiting the expression and activity of MMP-9 via NF-κB-dependent transcription." (PMID 25888829, 2015). "Direct targeting of MMP9 expression in invasive breast cancer cells was shown to significantly inhibit cell invasion and metastasis in vitro and in vivo." (PMID 25605249, 2015). "MMP-9 and MMP-13 are under the direct control of RUNX2 in a number of cell types, including breast cancer cells, and this was associated with invasive behavior of cancer cells." (PMID 26404249, 2015). "To demonstrate the functional consequence of glaucine in metastatic breast cancer, we used it to treat MDA-MB-231 cells, a highly metastatic breast cancer cell line that highly expresses MMP-9 and constitutively activated NF-κB." (PMID 25670016, 2015). "Elevated MMP-9/NGAL activity was found in breast cancer patients compared to healthy controls, and serum levels of MMP-9 and NGAL were significantly correlated with and breast disease severity score." (PMID 26663949, 2015). "MMP9 was exogenously expressed in breast cancer cells by transient transfection and assessed by PCR analysis of mRNA." (PMID 25605249, 2015). "Our data demonstrated that PinX1 inhibited breast cancer cells’ migration and invasion abilities by down-regulating MMP-9 expression and activity in vitro." (PMID 25888829, 2015). "Our results supports the role that iPLA2β regulates 4T1 breast cancer cell production of MMP-9, which is amplified by nicotine." (PMID 26588686, 2015). "Human breast cancer cell-produced MMP9 is specifically required for invasion in cell culture and for pulmonary metastasis in a mouse orthotopic model of basal-like breast cancer." (PMID 26674531, 2015). "In line with this, we found that several of the most upregulated genes in long-term EMT cells including Tnc, Mmp9, Jag1, and Ret, are known to promote breast cancer metastasis." (PMID 25674539, 2015). "Expression levels of MMP-9 in serum and tissue are significantly higher in patients with pancreatic ductal adenocarcinoma than in those with pancreatitis, and tumor MMP-9 expression is significantly elevated in patients with breast cancer." (PMID 25888323, 2015). "While pooled HR (95%CI) valued by multivariate analysis further verified the worse prognosis of MMP-9 positive in breast cancer patients." (PMID 26270045, 2015).
breast carcinoma (continued). "Taken together, our findings demonstrate that glaucine inhibits breast cancer cell migration and invasion by inhibiting NF-κB-mediated MMP-9 transcription." (PMID 25670016, 2015). "In conclusion, we provide novel evidence that glaucine suppresses breast cancer cell invasion and migration by inhibiting MMP-9 activity and expression, which was due to the blocking of NF-κB activation." (PMID 25670016, 2015). "The activity of MMP9 has also been shown to play a crucial role in breast cancer metastasis to the bone." (PMID 25605249, 2015). "The precise mechanism through which PRMT7 is acting to regulate MMP9 expression within breast cancer cells requires further elucidation." (PMID 25605249, 2015). "(v) A reciprocal interaction exists between integrin β1 and MMP-2/MMP-9 in metastatic breast cancer cells." (PMID 28721370, 2015). "Taken together our research suggests that nicotine exacerbates the severity of breast cancer through facilitating metastasis by enhancing MMP-9 production in an iPLA2β dependent manner." (PMID 26588686, 2015). "When the Ras/Raf/ERK pathway was blocked, MMP-9 expression was decreased, accompanied by attenuated proliferative and invasive capability of breast cancer cells." (PMID 26356670, 2015). "Taken together, it appears that EpCAM promotes breast cancer growth and invasion through regulation of MMP-9 expression." (PMID 26356670, 2015). "Taken together, these experiments demonstrate that PRMT7-regulated expression of MMP9 influences the invasive capabilities of breast cancer cells." (PMID 25605249, 2015). "Astrocytes have been shown to secrete matrix metalloproteinases (MMP), including MMP-2 and MMP-9, and that culturing metastatic breast cancer cells with astrocyte-conditioned media lead to increased invasive ability." (PMID 26180670, 2015). "Trx1 overexpression has been shown to promote breast cancer cell invasion by stimulating MMP-9 expression." (PMID 25945832, 2015). "We found that glaucine significantly inhibited MMP-9 gene expression by suppressing NF-κB activation, which subsequently reduced the invasion and migratory abilities of human breast cancer cells." (PMID 25670016, 2015). "This is the first report represents SENP5-TGFβ-MMP9 cascade and its mechanistic involvement in breast cancer." (PMID 24658161, 2014). "Pretreatment of the peptide with matrix-metalloproteinase 9 (MMP9) led to uptake of the digested peptide by MCF-7 breast cancer cells, which secrete only a low level of MMP-917, whereas the untreated peptide was not cell-permeable." (PMID 24811205, 2014). "Our objective was to investigate MMP-9 expression in normal human breast tissue and to compare it to that of breast cancer of various histological grades and molecular subtypes." (PMID 25151367, 2014). "Differential expression of MMP-9 reflects the extent of cellular differentiation in breast cancer cells and is closely related to the most aggressive subtypes of breast cancer." (PMID 25151367, 2014). "Taken together, our data underscore the role of MMP-9 in promoting breast cancer metastases in lymph node and lungs." (PMID 25151367, 2014). "To the best of our knowledge, we showed for the first time that suppression of integrin ανβ6 in MCF-7 human breast carcinoma cells dramatically reduced pro-MMP-9, pro-MMP-3 and uPA secretion in tumor conditioned medium." (PMID 25176506, 2014). "VEGF and MMP-9 are regarded as indispensable cytokines for breast cancer cell invasion and adhesion." (PMID 25299052, 2014). "To expand on the results obtained from the microarray datasets, we investigated mRNA expression of MMP-9 in 51 breast cancer cell lines of different molecular subtypes using publically available microarrays and mRNA sequencing breast cancer cell line datasets." (PMID 25151367, 2014). "Significant increase in MMP-9 expression was found in breast cancer cells where compared to normal breast tissue." (PMID 25151367, 2014).
breast carcinoma (continued). "Mean levels of serum VEGF and MMP-9 were significantly higher in the breast cancer patients when compared with the levels in the breast fibroadenoma patients and the healthy controls." (PMID 24944618, 2014). "In sharp contrast, only 16% of the luminal A breast cancer subtype demonstrate increased expression of MMP-9." (PMID 25151367, 2014). "We also sought to correlate MMP-9 expression with the incidence of metastasis, survival rates and relapse in breast cancer patients." (PMID 25151367, 2014). "Serum HER2, MMP-9, and carcinoma antigen 15-3 (CA 15-3) were assessed in 80 breast cancer patients and ten healthy subjects as a control group by the enzyme-linked immunosorbent assay (ELISA) technique while NO and TAC were assessed by a colorimetric method." (PMID 24634847, 2014). "In breast cancer, multiple large IHC studies have found MMP9 to be most consistently expressed by tumor cells, whereas MMP9 staining of stromal cells is rarer." (PMID 24811362, 2014). "Raf/MEK/ERK-mediated induction of gelatinase B/MMP-9 expression results in the destruction of breast tissue architecture, during breast cancer initiation, by degrading basement membrane laminin and destroying basement membrane integrity." (PMID 24473089, 2014). "Our goal was to assess the potential clinical usefulness of MMP-9 as a prognostic biomarker of breast cancer." (PMID 25151367, 2014). "MMP9 can be localized to the surface of murine mammary carcinoma cells via the hyaluronan receptor CD44, as a component of tumor cell invadopodia structures, where it can facilitate invasion and angiogenesis by proteolytic activation of latent TGF-β." (PMID 24811362, 2014). "MMP9-mediated gelatin matrix degradation showed substantially higher expression in PDBu-stimulated breast cancer cells expressing PFN and its mutants studied." (PMID 25084196, 2014). "Overexpression of MMP-9 in human breast cancer cells increases VEGF–VEGF receptor 2 complex formation and tumor angiogenesis." (PMID 25233229, 2014). "Preoperative levels of serum VEGF and MMP-9 were detected via a lipid chip-based method in 301 breast cancer cases, 83 breast fibroadenoma cases and 40 healthy adults." (PMID 24944618, 2014). "At any rate, our findings clearly emphasized the clinical potential of MMP-9 as a prognostic biomarker in breast cancer." (PMID 25151367, 2014). "Here, by manipulating tumor cell MMP9 expression in breast cancer cell lines and in an orthotopic mouse model of metastatic human breast cancer, we dissect the functional significance of tumor cell-produced MMP9 for invasion and metastasis." (PMID 24811362, 2014). "Increased tumor expression of MMP-1, MMP-2, MMP-7, or MMP-9 in lung cancers, and increased expression of MMP-1 and MMP-9 in breast cancer is associated with poor patient survival." (PMID 25491880, 2014). "We found that high expression of MMP-9 is specifically correlated with high-grade breast cancers that include both triple-negative and HER-2 positive breast cancers." (PMID 25151367, 2014). "FGF-1 has been reported to promote the invasion and metastasis of breast cancer by inducing MMP-9 expression." (PMID 25124967, 2014). "Many previous studies have been conducted to research MMP-9 expression in human cancers, including breast cancer, but the results are still controversial." (PMID 24993803, 2014). "Earlier results suggest that curcumin plays a role in regulating cell metastasis by inhibiting MMP-2 and MMP-9 in breast cancer cell line." (PMID 25295272, 2014). "PTL and its derivations have been shown to inhibit MMP-9 expression in breast cancer cells and prevent tumour metastasis." (PMID 25610476, 2014). "The expression of MMP-9 mRNA was high in breast cancer cells cultured with the media of normal HDFs, compared with that of the control media." (PMID 25013462, 2014). "Both MMP-9 and MMP-3 have been implicated to play a critical role in breast cancer invasion and metastasis in animal models and human patients." (PMID 25176506, 2014).
breast carcinoma (continued). "Fascin and MMP-9 expressions were detected in 43.28% and 50.75% of breast carcinomas (respectively)." (PMID 24993803, 2014). "MMP-9 expression was evaluated in 300 human tumor tissues representative of each molecular subtypes of breast cancer whose definition was based on the use of the following surrogate markers: ER, PR, HER2 and Ki-67." (PMID 25151367, 2014). "Serum levels of VEGF and MMP-9 were closely associated with tumor size (P<0.001), and the serum levels in patients with stage III or IV breast cancer were significantly higher than those classified as TNM stage I or II (P<0.001)." (PMID 24944618, 2014). "The elevated serum or plasma levels of MMP9 were observed in patients with colorectal, gastric, lung, and breast cancer but decreased levels were seen in patients with bone tumors and multiple myeloma and some breast cancers." (PMID 25469360, 2014). "Matrix metalloproteinase 9 (MMP-9) is a type-IV collagenase that is highly expressed in breast cancer, but its exact role in tumor progression and metastasis is unclear." (PMID 24845596, 2014). "In breast cancer, MMP-9 activity has been localized around CAFs and CAFs co-cultured with cancer cells which secrete TGF-β, TNF-α, and other cytokines, increase production of MMP-9, consistent with our in vitro data." (PMID 24586907, 2014). "The findings of this study provide the first evidence that ESL inhibits the TPA-induced expression of MMP-9 in MCF-7 breast cancer cells." (PMID 24885456, 2014). "MMP-9+ staining in breast cancer specimens (35/41, 85.4%) was higher than in matched epithelium (21/41, 51.2%; P<0.05) and lymph nodes (13/41, 31.7%; P<0.001)." (PMID 24845596, 2014). "We identified higher MMP-9 expression in breast cancer tissue than in benign peritumoral breast epithelium." (PMID 24845596, 2014). "While MMP9 expression in stromal cells has important prognostic implications in human breast cancer, the significance of the more substantial expression of MMP9 expression by tumor cells has not been clarified." (PMID 24811362, 2014). "Among these stimuli, TPA is a well-known selective activator of protein kinase C (PKC) and can stimulate MMP-9 synthesis and secretion in breast cancer cell invasion." (PMID 24885456, 2014). "To achieve that aim, we first studied MMP-9 mRNA expression using in silico analysis on available DNA microarray and RNA sequencing data of human breast cancer tissues and breast cancer cell lines." (PMID 25151367, 2014). "In the present paper, we provide both indirect and direct evidence that MMP-9 participates to breast cancer progression and impact on clinical outcome." (PMID 25151367, 2014). "MMP-9 was first studied using in silico analysis on available DNA microarray and RNA sequencing data of human breast cancer tissues and human breast cancer cell lines." (PMID 25151367, 2014). "An important study has shown in a human breast cancer xenograft model that administration of curcumin noticeably decreased metastasis to lung and suppressed the expression of NF-κB, MMP-9, COX-2, VEGF, and intercellular adhesion molecule-1." (PMID 25295272, 2014). "Additionally, MMP-9 is closely associated with tumor invasion and metastasis in a variety of human tumors, including lung adenocarcinoma, hepatocellular carcinoma, and prostate and breast cancers; furthermore, it was expressed in the serum and urine of patients with RCC." (PMID 24765179, 2014). "Here we performed in silico analysis of 1210 DNA microarrays of human breast cancer tissues and RNA sequencing data of 51 human breast cancer cell lines to assess MMP-9 mRNA expression." (PMID 25151367, 2014). "Taken together, our findings suggest that the differential expression of MMP-9 contributes to breast cancer heterogeneity and is a key characteristic of the “molecular signature” of subsets of breast cancer." (PMID 25151367, 2014).